C1S (complement C1s)
Description:
Component of the complement C1 complex, a multiprotein complex that initiates the classical pathway of the complement system, a cascade of proteins that leads to phagocytosis and breakdown of pathogens and signaling that strengthens the adaptive immune system. C1S is activated following association of the C1 complex with immunoglobulins (IgG or IgM) complexed with antigens to form antigen-antibody complexes on the surface of pathogens. C1S is cleaved and activated by C1R to generate C1s subcomponent heavy and light chains. C1s subcomponent light chain then cleaves and activates C2 and C4, the next components of the classical complement pathway. [Complement C1s subcomponent light chain]: Serine protease component of the complement C1 complex, which catalyzes cleavage and activation of C2 and C4, the next components of the classical complement pathway. Also able to cleave C1 inhibitor (SERPING1) in vitro; additional evidence is however required to confirm this result in vivo. Also cleaves IGFBP5 and thereby inhibits the trophic effects of IGF1.
Synonyms: EDSPD2
Tractability: Small molecule: a structure with a bound ligand is known; a high-quality ligand is known; it belongs to a druggable protein family. Antibody: an approved drug acts on it; UniProt places it where antibodies can reach, with high confidence; its Gene Ontology location is reachable by antibodies, with high confidence; UniProt predicts a signal peptide or a membrane-spanning region. PROTAC: its protein half-life has been measured; a small molecule that binds it is known. Other modalities: an approved drug acts on it.
Target class: Serine protease; Enzyme; Serine protease PA clan; Serine protease S1A subfamily; Protease
Gene: Protein-coding gene on chromosome 12 (6,988,259 to 7,071,281, forward strand). Ensembl gene ENSG00000182326.
Subcellular location: Secreted; Cell surface
Subcellular location (Human Protein Atlas): Nucleoplasm; Cytosol; Predicted to be secreted
Pathways (Reactome):
Immune System: Classical antibody-mediated complement activation; Initial triggering of complement; Regulation of Complement cascade
Disease: Dengue virus activates/modulates innate and adaptive immune responses
Gene Ontology:
Molecular function: identical protein binding; protein binding; serine-type endopeptidase activity; calcium ion binding
Biological process: complement activation, classical pathway; complement activation; proteolysis
Cellular component: blood microparticle; cell surface; complement component C1 complex; extracellular region; symbiont cell surface
Genetic constraint (gnomAD): Loss-of-function variants: 24 observed, 43.12 expected, observed/expected ratio (o/e) 0.56, 90% interval 0.4 to 0.78. The upper end of that interval is the gene's LOEUF score, 0.78, which puts it in group 3 of 6, group 1 being the genes least tolerant of losing a copy. Missense variants: 684 observed, 843.68 expected, observed/expected ratio (o/e) 0.81, 90% interval 0.76 to 0.86. Synonymous variants: 282 observed, 305.37 expected, observed/expected ratio (o/e) 0.92, 90% interval 0.84 to 1.02.
Homologues: Orthologues: chimpanzee C1S (99% identical), macaque C1S (94% identical), dog C1S (80% identical), rabbit C1S (79% identical), pig C1S (79% identical), mouse C1s2 (75% identical), mouse C1s1 (74% identical), rat C1s (73% identical), guinea pig C1S (72% identical), tropical clawed frog c1s (50% identical), zebrafish c1s.2 (22% identical). Paralogues in human: C1R (39% identical), C1RL (22% identical), HGFAC (18% identical), KLKB1 (18% identical), F11 (17% identical), F7 (17% identical), HP (17% identical), HPR (16% identical), F12 (16% identical), F9 (16% identical), F10 (15% identical), CFI (15% identical), and 4 more.
Diseases named in the same sentence as C1S in open-access papers:
C1S is named in the same sentence as 150 diseases in open-access papers, as found by Europe PMC text mining. Sharing a sentence is not in itself a finding about the gene and the disease. The quoted sentences say what the papers report.
hereditary angioedema (59 papers, 2008 to 2026). Hereditary angioedema (HAE) is a genetic disease characterized by the occurrence of transitory and recurrent subcutaneous and/or submucosal edemas resulting in swelling and/or abdominal pain. "Regarding C1s/C1-INH, levels were increased 2-3-fold in Hereditary angioedema (HAE) patients when compared to controls." (PMID 36420270, 2022).
COVID-19 (17 papers, 2020 to 2025). A disease caused by infection with severe acute respiratory syndrome coronavirus 2. "Overall, these results show that the biomarkers PTX3, sMR and, to a lesser extent, C1-INH and C1s/C1-INH are associated with disease severity in this COVID-19 patient cohort." (PMID 39027374, 2024). "Our results suggest that COVID-19 is causing upregulation of IgG production leading to activation of classical complement through C1S, which produces a downregulation of RUNX1 and TYK2 signaling, that blocks T-cell maturation and mutes Th1/Th17 immune response, respectively." (PMID 34899680, 2021). "The gene C1S, associates with two other complement components C1r and C1q in order to yield the C1 complex, which then triggers the subsequent steps of the classical pathway of complement activation, and is found to be upregulated in the lungs of severe COVID-19 patients in our IPA analysis." (PMID 34899680, 2021). "As excessive macrophages activation is a hallmark of COVID-19 and complement activation is key in this, we selected the following proteins involved in these processes: PTX3, C1q, C1-INH, C1s/C1-INH, and sMR." (PMID 39027374, 2024). "Neutrophils from patients with severe COVID-19 were characterized by increased detection of classical complement pathway components, such as C1R and C1S." (PMID 34403366, 2021). "Upregulation of C1s (1.60-fold), C1q (1.53-fold), C2 (2.76-fold), C3 (1.9-fold), and C4b (2.45-fold) indicated that timely complement activation may contribute to COVID-19 in CMs." (PMID 35903092, 2022). "Measurements showed increased C1-INH complex levels in COVID-19 patients when compared to healthy controls, with a mean concentration of 2407 ± 1283 ng/mL C1s/C1-INH complex (Mann-Whitney U test: p<0.0001) and 51.5 (33.5-76.1) ng/mL MASP-1/C1-INH complex (Mann-Whitney U test: p<0.0001)." (PMID 36420270, 2022). "Self-made C1 complex (C1q, C1s, C1r) can translocate to the monocyte cell surface and activate the complement cascade, thus suggesting a possible role for monocyte-driven classical complement activation during COVID-19." (PMID 35250994, 2022). "In that light, also C1-INH and C1s/C1-INH complex were selected as they are located directly downstream of PTX3 and C1q and also involved in COVID-19 pathogenesis." (PMID 39027374, 2024). "The newly developed assays were used to measure C1s/C1-INH complex and MASP-1/C1-INH complex levels in healthy individuals (n=96) as well as in a total of 414 COVID-19 patients." (PMID 36420270, 2022). "The gene expression and functional analysis of the early vs. late COVID-19 cases revealed significant differences with increased levels of ADAM17, C1S, SERPING1, and DDIT3 in the early group." (PMID 35163504, 2022). "Clusters A to C contain proteins with lower levels in COVID-19 convalescents, e.g. proteins functioning in cell adhesion and platelet degranulation (e.g. fibrinogen A (FGA), VWF), and innate immunity/the complement system (e.g. C1R, C1S, C1QA, C1QC, and GGH)." (PMID 38396092, 2024). "This study also found increased C1r and C1s, the proteases inhibited by C1-INH, in COVID-19." (PMID 34458849, 2021).
systemic lupus erythematosus (12 papers, 2015 to 2025). An autoimmune multi-organ disease typically associated with vasculopathy and autoantibody production. "Paradoxically, patients with homozygous deficiency of the CP components, including C1 (C1q, C1r, or C1s), C4, or C2, have a high risk of lupus or lupus-like disease." (PMID 29892304, 2018). "However, the pathological impact of C1S genetic deficiencies, such as severe lupus or periodontal EDS, cannot be simply explained only by considering this function, therefore suggesting auxiliary non-canonical functions for this protease." (PMID 37180096, 2023). "While deficiency of C1s is associated with early-onset systemic lupus erythematosus and increased susceptibility to bacteria infections, the gain-of- function variants of C1r and C1s may lead to periodontal Ehlers Danlos syndrome." (PMID 36275687, 2022). "Both genes encoding C1s and C1r are located on the short arm of chromosome 12 and several deleterious mutations, resulting in no detectable protein in the serum, have been identified in patients with lupus-like phenotype." (PMID 30459768, 2018). "Therefore, deficiencies of C1q, C1r, C1s, C2, or C4 have been strongly associated with both immunodeficiency as well as autoimmunity, including lupus-like phenotype." (PMID 30459768, 2018). "For example, ficolins and the C1 complex (C1q, C1r, and C1s) detect danger molecules produced by stressed and dying cells, such as surface blebs on apoptotic cells, and deficiencies or dysfunctions in C1 proteins are associated with the autoimmune disease systemic lupus erythematosus (SLE)." (PMID 28149297, 2017). "Among the strongest, known genetic risk factors for the development of systemic lupus erythematosus (SLE) are deficiencies of the classical complement pathway components (C1q, C1r, C1s, C4, or C2)." (PMID 25688346, 2015). "It has been demonstrated that C1s deficiency was associated with ICR-Derived Glomerulonephritis (ICGN) and systemic lupus erythematosus." (PMID 32821246, 2020). "KEGG analysis revealed the systemic lupus erythematosus pathway involving CD86, TNF, C4, FCGR2B, CD80, C3, CD40, and C1S." (PMID 28976997, 2017). "In addition, several autoimmunity-related proteins are linked to coagulation (e.g., AGT, F2) and to specific ADs, such as systemic lupus erythematosus (e.g., AGT, C1S, C7, MMP2, VWF) or autoimmune rheumatic diseases (e.g., ADIPOQ, AGT, MASP1, MMP2)." (PMID 40546301, 2025).
autoimmune disease (9 papers, 2014 to 2024). A disorder resulting from loss of function or tissue destruction of an organ or multiple organs, arising from humoral or cellular immune responses of the individual to their own tissue constituents. "In contrast, complete deficiency of C1r or C1s caused by homozygous C1R- or C1S-null mutations causes a lupus-erythematosus-like syndrome with increased susceptibility to infections and increased risk of developing autoimmune diseases." (PMID 27745832, 2016). "The critical roles of the complement system in innate and acquired immunity make the activation of C1s an informative biomarker for a variety of diseases, particularly the inflammatory, autoimmune diseases and cancers." (PMID 36275687, 2022). "Interestingly, C1s can cleave high-mobility group box 1 (HMGB1) protein, a notable auto-antigen in autoimmune diseases." (PMID 36275687, 2022).
Autoimmunity (8 papers, 2009 to 2023). The occurrence of an immune reaction against the organism's own cells or tissues. "Whether this function requires the C1r and C1s subunits is unclear, but deficiencies in a subunit of C1q can increase susceptibility to autoimmunity." (PMID 19379516, 2009). "This is part of the classical pathway, in which the activation of C1s triggers the formation of a membrane complex to promote inflammation and autoimmunity." (PMID 37886940, 2023). "In this context, the four earliest components of the complement classical pathway, i.e., C1q, C1r, C1s, and C4, may be considered as an essential albeit insufficient tolerance mechanism against dead cell-induced autoimmunity." (PMID 37359557, 2023). "C1s appears to show nearly four-fold higher proteolytic activity in the presence of anti-C1s antibody, thus contributing to the amplification of the complement-dependent cellular lysis, and availability of autoantigens, and hence, the possible development of autoimmunity." (PMID 36012546, 2022). "However, cleavage of these non-complement and complement proteins by C1s does not provide a biological plausible explanation to its protective role against the development of autoimmunity." (PMID 27648302, 2016).
Periodontal Ehlers-Danlos Syndrome (8 papers, 2016 to 2023). "Periodontal EDS—Recently, heterozygous pathogenic gain-of-function variants in the C1R and C1S genes, encoding the C1r and C1s subunits of the first component of the classical complement pathways, were associated with periodontal EDS (pEDS)." (PMID 35205310, 2022). "Periodontal EDS is a distinct clinical entity that we have now shown to be caused by mono-allelic missense or in-frame insertion/deletion alterations in C1R or C1S, the genes that encode complement 1 subunits C1r and C1s." (PMID 27745832, 2016). "We previously identified heterozygous missense mutations in the C1R and C1S genes, coding for the complement C1 proteases, in patients affected by periodontal EDS, a specific EDS subtype hallmarked by early severe periodontitis leading to premature loss of teeth and connective tissue alterations." (PMID 31921203, 2019). "Periodontal Ehlers-Danlos syndrome (pEDS) is a rare subtype of EDS with autosomal-dominant inheritance caused by mutations in two linked genes, C1R and C1S, which encode complement 1 subunits C1r and C1s." (PMID 36237549, 2022). "Additionally, the C1q subunit—binding partner of the C1s-C1r tetramer—has a triple helical structure, which resembles collagen; some features of periodontal EDS may be due to abnormal C1r/C1s interaction with extracellular matrix components." (PMID 30535813, 2019).
Ehlers-Danlos syndrome (7 papers, 2017 to 2023). The Ehlers–Danlos syndromes (EDS) are a clinically and genetically heterogeneous group of heritable connective tissue disorders (HCTDs) characterized by joint hypermobility, skin hyperextensibility, and tissue fragility. "Cell type-specific expression patterns confirmed fibroblast as particularly high expressors of the C1S and C1R gene, mutated in Ehlers-Danlos syndrome, periodontal type." (PMID 34566966, 2021). "In monogenic Ehler Danlos Syndrome the alterations in C1R or C1S genes encoding for complement 1 subunits C1r and C1s has been documented as a link between connective tissue pathology with classical complement pathway." (PMID 29760828, 2018). "Our interest in this disease context opened through a collaboration with scientists from Innsbruck Medical University, who discovered heterozygous mutations in C1 subunit genes C1R and C1S, which were clearly associated with a specific periodontal subtype of Ehlers-Danlos Syndromes (EDS)." (PMID 35572583, 2022). "Furthermore, C1r and C1s heterozygous mutations in periodontal Ehlers-Danlos syndrome (pEDS) suggest a gain of function of C1s which could be deleterious in collagen tissue homeostasis as well as in periodontal tissue maintenance." (PMID 37180096, 2023).
cold agglutinin disease (6 papers, 2019 to 2025). Cold agglutinin disease is a type of autoimmune hemolytic anemia defined by the presence of cold autoantibodies (autoantibodies which are active at temperatures below 30B0C). "This group included 10 patients on complement inhibitors: 7 paroxysmal nocturnal hemoglobinuria on C5 inhibitor eculizumab/ravulizumab (N = 6) or on oral factor B inhibitor (N = 1), and 3 cold agglutinin disease on C1s inhibitor sutimlimab." (PMID 35634287, 2022). "Antibodies against C1s are being used successfully to suppress CP-triggered cold-agglutinin disease and might reasonably have efficacy in preventing atheroma formation." (PMID 31555668, 2019).
glioblastoma (5 papers, 2017 to 2024). The most malignant astrocytic tumor (WHO grade IV). "As reported by research on U87 and T98G cell lines, knockdown of complement C1s significantly reduces cell viability and inhibits cell migration and invasion, indicating that complement C1s promotes glioblastoma cell proliferation." (PMID 39071493, 2024). "Analysis of the function of C1S revealed that downregulation of C1S contributed to the inhibition of proliferation, migration, and invasion of glioblastoma cell lines." (PMID 33579282, 2021). "Among them, the MIR155HG/has-miR-129-5p/C1S axis is a potential marker and therapeutic target for glioblastoma." (PMID 33579282, 2021). "In functional assays, knockdown of C1S inhibited the proliferation and invasion of glioblastoma cell lines." (PMID 33579282, 2021). "In synchrony with these findings, human glioblastoma tumor samples have been shown to demonstrate upregulation of the C1 complex proteins (C1q, C1s) as well as C1-INH protein." (PMID 34671342, 2021). "The same pattern of upregulation of the components of the C1 complex was observed as in the Affymetrix data and C1s (fold change 4.7; p = 0.027) and C1qβ(fold change 8.7; p = 0.011) were upregulated in glioblastoma patients as compared to controls." (PMID 28880870, 2017). "While the role of C1s in tumors such as skin squamous cell carcinoma, glioblastoma, and urothelial carcinoma has been confirmed, its role in ESCC remains unclear." (PMID 39071493, 2024). "Knockdown of C1S inhibited the proliferation, migration, and invasion of glioblastoma cells." (PMID 33579282, 2021). "Additionally, an MTS assay and the wound-healing and transwell assays were performed to evaluate the effects of complement C1s (C1S) on the viability and migration and invasion abilities of glioblastoma cells, respectively." (PMID 33579282, 2021). "The gene analysis revealed increased expression of C1q and C1s in glioblastomas." (PMID 28880870, 2017). "Like C1r and C1s, C1q is also upregulated in response to the increased levels of C1-INH in glioblastoma." (PMID 34671342, 2021). "That is, C1q (fold change 4.2; p < 0.001), C1s (; fold change 4.0; p < 0.001) and C4a (fold change 2.1; p < 0.001) were significantly up-regulated in material from patients with glioblastoma as compared to non-tumor controls." (PMID 28880870, 2017).
lung carcinoma (5 papers, 2019 to 2025). "As matter of secretome profiling and IPA prediction, the Fibronectin, C1r, and C1s are potential of nephrotoxicity linked to paraneoplastic effects on glomerular pathogenesis in these lung cancer mice." (PMID 33260558, 2020). "In vitro, lung cancer cells produced C5a independently of the expression of factor B, properdin, C1q, C1r, C1s, C1, and C4." (PMID 40370471, 2025). "In many tumor types (lung cancer, breast cancer, pancreatic cancer, kidney cancer), complement proteins C1q, C1s, C3, C4, anaphylatoxins C3a and C5a and their receptors and regulatory proteins (such as factor B, factor H, factor I, CD55 and CD59) are most often overexpressed." (PMID 40596619, 2025).
viral infection (5 papers, 2017 to 2025). "In present study, the increase in complement system initiation factors (C1s), chemotactic factors and acute phase proteins, and decrease of anti-inflammatory factors positively regulated the damage response and inflammatory response caused by viral infection." (PMID 29073194, 2017). "In our current study, we observed that increased expression of classical pathway protein C1s and alternative pathway protein Factor B during viral infection." (PMID 32566414, 2020). "The CXCL10/11high basal cells also had upregulated mRNA encoding for complement components (C1R and C1S), MHC class I (HLA-A, HLA-B, HLA-C, and B2M), and metalloproteases MMP2 and MMP13, the latter reducing repair during viral infection in bronchial epithelial cells." (PMID 40980495, 2025). "For example, the NS1 glycoprotein of some Flaviviruses (i.e. Dengue, West Nile and Yellow fever), which is expressed on the surface of and secreted by infected cells, can suppress complement by recruiting and activating C1s and C4BP to promote cleavage of C4 and inactivate C4B." (PMID 30774579, 2019).